GALC (galactosylceramidase)
Diseases named in the same sentence as GALC in open-access papers (continued):
Sharing a sentence is not in itself a finding about the gene and the disease.
Krabbe disease (continued). "Krabbe disease is an autosomal‐recessive disorder resulting from a deficiency of the enzyme galactosylceramidase (GALC) 1, 2, which degrades galactosylceramide and psychosine generated during the process of active myelination." (PMID 28170189, 2017). "Krabbe's disease is a sphingolipidosis caused by the deficiency of galactosylceramidase (GALC) activity." (PMID 28531236, 2017). "Krabbe disease (KD) or globoid cell leukodystrophy (GLD) is due to autosomal recessive mutations in GALC, a lysosomal enzyme that catalyzes the hydrolysis of GalCer and galactosylsphingosine." (PMID 29163032, 2017). "Krabbe disease, or globoid cell leukodystrophy, is a rare disorder caused by deficient galactosylceramidase activity and loss of myelin‐forming oligodendrocytes, resulting in progressive demyelination and severely impaired motor function." (PMID 28170189, 2017). "Krabbe disease leads to severe neurological manifestations and is linked to a galactosylceramidase (GALC) deficiency." (PMID 27625992, 2016). "Krabbe disease is caused by defects in the lysosomal enzyme galactocerebrosidase (GALC) that is essential for the catabolism of galactosphingolipids, including the primary lipid component of myelin, galactocerebroside." (PMID 27126738, 2016). "Krabbe disease (KD) is an autosomal recessive neurodegenerative disorder caused by defective β-galactosylceramidase (GALC), a lysosomal enzyme responsible for cleavage of several key substrates including psychosine." (PMID 27780934, 2016). "ß-Galactosylceramidase (GALC) deficiency in Krabbe disease (KD) patients leads to the accumulation of its substrates galactosylceramide (GalCer) and psychosine." (PMID 27780934, 2016). "Because of the severe deficiency of GALC activity in affected mice, the twitcher mouse is considered to be a valuable model for clinical trials for the treatment of Krabbe disease." (PMID 25888852, 2015). "GALC encodes the enzyme β-galactocerebrosidase, mutations in which are responsible for Krabbe disease." (PMID 26569114, 2015). "New insights come also from the Twitcher mouse, a naturally occurring model of Krabbe disease, characterized by deficiency of galactosylceramidase (GALC)." (PMID 24432014, 2014). "One such example of LSDs with fatal manifestations includes globoid-cell leukodystrophy (GLD) or Krabbe disease in which mutations in galactosylceramidase leads to accumulation of the toxin “psychosine” in the CNS." (PMID 25285067, 2014). "The Twitcher mouse is a model for the Krabbe disease, characterized by the deficiency of galactosylceramidase (GALC), a lysosomal enzyme that hydrolyzes the terminal galactose from galactosylceramide, a typical component of the myelin membrane." (PMID 24432014, 2014). "The Twitcher mouse model was developed through spontaneous mutation of the GALC gene at the Jackson Laboratory in 1976 and shares many neuropathologic findings with the human infantile type of Krabbe disease." (PMID 23590629, 2013). "Krabbe disease is an autosomal recessive lysosomal storage disorder caused by mutations in the GALC gene." (PMID 22704718, 2012). "Case 2 was a one-year-old Caucasian female reported to have deficient GALC enzyme activity by blood assay and by fibroblast assay, and clinical features consistent with Krabbe disease." (PMID 22704718, 2012). "They investigated globoid cell leukodystrophy (Krabbe disease), caused by a deficiency of galactosylceramidase, and found increased concentrations of galactosylsphingosine (psychosine) in post-mortem brain tissue." (PMID 21299873, 2011). "Among all the GALC mutations causing Krabbe disease, the most common in Caucasian individuals (40–45%) is the large 31-kb deletion beginning in intron 10 and continuing past the end of GALC." (PMID 22073273, 2011). "Homozygous deletions that eliminate GALC enzymatic activity cause Krabbe disease, a recessive Mendelian disorder of childhood displaying bilateral optic neuropathy and vision loss." (PMID 22073273, 2011).
Krabbe disease (continued). "This study, reporting one of the largest genotype-phenotype analyses of the GALC gene so far performed in a European Krabbe disease cohort, revealed that the Italian GALC mutational profile differs significantly from other populations of European origin." (PMID 20886637, 2010). "This study therefore reports one of the largest mutational analyses of the GALC gene so far performed in a Caucasian population affected by Krabbe disease." (PMID 20886637, 2010). "The characterization of the underlying GALC gene lesions was performed in 30 unrelated patients affected by Krabbe disease, an autosomal recessive leukodystrophy caused by the deficiency of lysosomal enzyme galactocerebrosidase." (PMID 20886637, 2010). "Moreover, it was demonstrated in fibroblasts, as well as in leukocytes, from patients with the Thr112Ala variant that the enzymatic activity of GALC is reduced and thereby can lead to an infantile onset of Krabbe disease." (PMID 40943566, 2025). "As the Thr112Ala mutation caused Krabbe disease, we first analyzed the active site of GALC." (PMID 40943566, 2025). "Thus, not only mutations directly affecting the enzymatic activity of GALC cause Krabbe disease but also mutations affecting the localization." (PMID 40943566, 2025). "Therefore, understanding the molecular basis of GALC dysfunction in Krabbe disease is critical for advancing both diagnostic and therapeutic approaches." (PMID 40943566, 2025). "This might affect the substrate affinity of the enzyme, which would result in reduced activity, explaining on a molecular level how the Thr112Ala mutation in GALC causes Krabbe disease." (PMID 40943566, 2025). "This suggested mode of action of the Thr112Ala mutation is different compared to other known mutations causing Krabbe disease: The mutation D528N has a minor influence on the enzymatic activity but leads to misfolding of GALC due to a second N-glycosylation side." (PMID 40943566, 2025). "Homozygous or compound heterozygous loss of function variants in GALC are associated to Krabbe diseases (KD, MIM #245200), a lysosomal disorder affecting the white matter of the central and peripheral nervous systems with variable age of onset (i.e., childhood, juvenile and adult)." (PMID 40208338, 2025). "Patients diagnosed with Krabbe disease often harbor compound heterozygous mutations in the GALC gene with unknown influence on GALC activity." (PMID 40943566, 2025). "Advancements in genomic technologies, including whole-exome and whole-genome sequencing, have accelerated the identification of pathogenic variants in lysosomal genes such as GBA (associated with Parkinson’s disease), GALC (Krabbe disease), and GLA (Fabry disease)." (PMID 41614773, 2025). "Metachromatic leukodystrophy is due to lack of arylsulfatase A, resulting in accumulation of the sphingolipid sulfatide, while Krabbe disease is caused by deficiency in galactosylceramidase, with consequent accumulation of galactosylceramide and galactosylsphingosine (psychosine)." (PMID 40552465, 2025). "Krabbe disease (KD) is associated with genetic mutations and subsequent loss of function of the acid hydrolase galactosylceramidase (GalC) enzyme, which plays a key role in metabolism of galactosylceramide and the toxic galactolipid galactosylsphingosine (psychosine)." (PMID 38558359, 2024). "Mutations in GALC are typically associated with Krabbe Disease (OMIM 245200), a rare autosomal recessive disorder characterized by absence of myelin, severe gliosis, and other neurodegenerative symptoms resulting from the accumulation of toxic myelin breakdown product." (PMID 38370976, 2024). "Moreover, the study identified three patients with compound heterozygous CBS mutations causing homocystinurias, compound heterozygous DPYD mutations causing DPD deficiency, and homozygous GALC mutations causing Krabbe Disease, respectively." (PMID 37237429, 2023).
Krabbe disease (continued). "Krabbe disease (KD), also known as globoid cell leukodystrophy, is a rare autosomal recessive disease caused by mutations in the galc gene, which codes for the enzyme galactosylceramidase (GALC)." (PMID 37238985, 2023). "Due to the clear evidence that this disease is caused by the functional deficiency of GALC, gene therapy for GALC may be a direct and promising treatment approach for Krabbe disease." (PMID 37111381, 2023). "Globoid cell leukodystrophy or Krabbe disease is an autosomal recessive disorder caused by biallelic pathogenic variants in GALC (MIM# 245200) or PSAP (MIM# 611722) that leads to the deficiency of the enzyme galactocerebrosidase, or its activator protein saposin." (PMID 37564735, 2023). "Microglia/macrophages principally undertake this clearance; for receptor-mediated phagocytic removal, myelin binds to surface receptors either directly or after opsonization, but clearance of degenerated myelin cannot proceed effectively in Krabbe disease because of GALC deficiency in these cells." (PMID 36519759, 2023). "His GALC enzyme level was markedly decreased at 0.06 nmol/h/mg of protein and his GALC mutation analysis showed homozygosity for the 30 kb deletion of the C-terminal end of the GALC gene establishing a diagnosis of Krabbe disease." (PMID 35966016, 2022). "Krabbe disease is a lysosomal storage disease caused by mutations in the gene that encodes galactosylceramidase, in which galactosylsphingosine (psychosine) accumulation drives demyelination in the central and peripheral nervous systems, ultimately progressing to death in early childhood." (PMID 35333110, 2022). "Human PLAs (specifically isoforms of PLA2) have been recently implicated in myelin degenerative diseases, e.g., Krabbe disease, a fatal inherited lipid disorder linked to toxic accumulation of galactosylceramidase (psychosine), which induces cell death of astrocytes and oligodendrocytes." (PMID 35447967, 2022). "Krabbe Disease (KD) is an autosomal recessive disorder that results from loss-of-function mutations in the GALC gene, which encodes lysosomal enzyme galactosylceramidase (GALC)." (PMID 36113749, 2022). "Also, homozygous mutations in GBA and GALC impair clearance of HexCer, namely gluco- and galactosylceramides, and cause Gaucher’s and Krabbe’s disease, respectively." (PMID 35351864, 2022). "Krabbe disease (KD), also known as globoid cell leukodystrophy, is a rare lysosomal storage disorder caused by deficiency of galactocerebrosidase (GALC) leading to generation of psychosine, a cytotoxic agent that causes loss of oligodendrocytes and Schwann cells." (PMID 33801069, 2021). "GALC SNPs are now known to be a significant cause of Krabbe disease (KD)." (PMID 34045940, 2021). "Krabbe’s disease is a genetic disease characterized by extensive demyelination, apoptosis of oligodendrocytes and Schwann cells and neurodegeneration due to mutations in the GALC gene that encode for galactocerebrosidase." (PMID 34202192, 2021). "Krabbe disease (KD) is a leukodystrophy caused by mutations in the galactosylceramidase gene." (PMID 34900869, 2021). "Krabbe’s disease (KD) or globoid cell leukodystrophy (GLD) is an autosomal recessive pathology caused by genetic defects in the lysosomal enzyme galactosylceramidase (GALC)." (PMID 34480290, 2021). "Recessive mutations in the galactosylceramidase (GALC) gene cause Krabbe disease (KD), also known as globoid cell leukodystrophy or galactosylceramide lipidosis, which is a rare, often fatal LSD resulting in progressive damage to the white matter of the peripheral and central nervous system." (PMID 32375870, 2020). "Finally, for the third sphingolipidosis diagnosed in this patient set, we found a pathogenic variant in GALC gene in a patient with clinical picture of Krabbe disease (patient P6)." (PMID 32883051, 2020).
Krabbe disease (continued). "Globoid cell leukodystrophy, or Krabbe disease, is a congenital disorder caused by mutations in the galactosylceramidase gene, GALC, and is characterized by psychomotor regression, muscular hypertonia, muscular spasticity, truncal hypotonia, irritability, seizures, and nystagmus." (PMID 32498325, 2020). "Krabbe disease is an LSD that results from the loss of GALC activity in myelin-producing cells, and as NSCs already promote oligogenesis, we reasoned that constitutively overexpressing GALC through HR in NSC safe harbor loci would improve their therapeutic potential." (PMID 31132746, 2019). "However, this does not reflect the specificity of saposins in whole organisms as loss of SapA causes Krabbe disease, similar to that of loss of GALC, while mutations in SapC do not20,21,23–25." (PMID 31667358, 2019). "Krabbe disease (KD), or globoid cell leukodystrophy, is an autosomal recessive sphingolipidosis caused by the deficiency of the lysosomal hydrolase β-galactosylceramidase (GALC) (EC 3.2.1.46)." (PMID 31905906, 2019). "Krabbe disease (KD) is an autosomal recessive, neurodegenerative disease caused by deficiency of the lysosomal enzyme galactocerebrosidase (GALC), which is essential for myelin turnover and is encoded by the GALC gene." (PMID 29391017, 2018). "Krabbe disease is associated with mutations in the galc gene encoding for the enzyme galactosylceramidase (GALC) resulting in the build-up of one particular galactolipid, called psychosine, which is suspected to be responsible for the pathology of this illness." (PMID 29095858, 2017). "In order to better understand the underlying molecular mechanisms causing GALC dysfunction in Krabbe disease, clinically relevant variants of GALC were expressed in cells and monitored for their capacity to traffic beyond the ER‐TGN and to localize to their site of action in lysosomes." (PMID 27126738, 2016). "Krabbe disease (KD) characterized by globoid cell leukodystrophy is an autosomal recessive lysosomal storage disease caused by mutations in the β-galactosylceramidase (GALC) gene that impair the enzymatic function." (PMID 27780934, 2016). "Krabbe disease (KD; also known as globoid cell leukodystrophy) is an autosomal recessive sphingolipidosis with a severe and progressive neurodegenerative disease course caused by deficiencies in the lysosomal hydrolase β‐galactocerebrosidase (GALC)." (PMID 27638604, 2016). "Over 100 different mutations have been identified in GALC that cause Krabbe disease but the mechanisms by which they cause disease remain unclear." (PMID 27126738, 2016). "These mutations may help to enrich the GALC pathogenic mutation database and increase public awareness of Krabbe disease in Morocco." (PMID 26567009, 2015). "GALC encodes galactosylceramidase, which is related to globoid cell leukodystrophy in humans." (PMID 26332579, 2015). "Krabbe disease, also known as globoid cell leukodystrophy, is an autosomal recessive neurodegenerative disease caused by the genetic deficiency of galactocerebrosidase (GALC), a lysosomal enzyme responsible for the degradation of several glycosphingolipids like psychosine and galactosylceramide." (PMID 23590629, 2013). "Krabbe disease (KD) (OMIM 245200), also known as globoid cell leukodystrophy (GLD), is an autosomal recessive lysosomal storage disorder caused by mutations in the GALC gene, which encodes a lysosomal galactocerebrosidase." (PMID 41414721, 2025). "Also known as globoid cell leukodystrophy, Krabbe disease is an autosomal recessive disorder characterized by the deficiency of the acid hydrolase β-galactosylceramidase (GALC) encoded by the GALC gene." (PMID 36902174, 2023). "Krabbe disease, also known as globoid cell leukodystrophy (GLD), is caused by mutations of galactosylceramidase (GALC), an enzyme responsible for hydrolyzing galactolipids, including galactosylceramide and psychosine (galactosylsphingosine)." (PMID 36675224, 2023).
Krabbe disease (continued). "As a previous example of the way to overcome this challenge, the chimeric GALC enzyme tethered to the lysosomal membrane has been engineered in the Krabbe disease mouse model so the cell-autonomous effect of oligodendrocyte-specific GALC deficiency could be studied." (PMID 35444603, 2022). "Globoid cell leukodystrophy (GLD or Krabbe disease) is a monogenic lysosomal storage disorder (LSD) caused by the deficiency of β-galactocerebrosidase protein (GALC)." (PMID 21809420, 2011). "In the second classic genetic leukodystrophy—globoid cell leukodystrophy, or Krabbe disease, there are genetic defects in a lysosomal hydrolase, galactosylceramidase, which catabolizes the myelin sphingolipid galactosylceramide." (PMID 40940747, 2025). "In globoid cell leukodystrophy, codon optimization of galactocerebrosidase (GALC) enabled safe and effective HSPC gene therapy in murine models." (PMID 40806226, 2025). "Krabbe disease (KD, OMIM # 245200) is an LSD caused by mutations in the GALC gene, leading to a deficiency of galactocerebrosidase (GALC) and accumulation of the glycolipids galactosylceramide (GalCer) and sulfatide." (PMID 41306917, 2025). "Therefore, mutations affecting the binding of GALC to saposin A might also cause Krabbe disease." (PMID 40943566, 2025). "A detailed workflow for recombinant GALC production and characterization is presented to support enzyme replacement therapy for Krabbe disease." (PMID 40590240, 2025). "LUNAR-hGALC mRNA was injected into the unilateral striatum of the Krabbe disease model mice (a GALC-deficient mouse, Galc−/−, twitcher mice) at postnatal day 1 (P1)." (PMID 39640012, 2024). "Krabbe Disease (Kd), also known as globoid cell leukodystrophy, is a lysosomal storage disease (LSD) cause by mutations in the GALC gene which encodes the lysosomal hydrolase galactosyl ceramidase (GALC)." (PMID 39636943, 2024). "Matsuzawa and colleagues reported that LUNAR lipid nanoparticles (LNPs) effectively and specifically introduced mRNA into oligodendrocytes, and LUNAR-human GALC mRNA improved phenotype and survival in a mouse model of Krabbe disease." (PMID 39640012, 2024). "In Fabry disease and Krabbe disease, mutations in the degrading enzymes alpha-galactosidase (GLA) and galactocerebrosidase (GALC) both lead to cardiomyopathy." (PMID 36742461, 2023). "In Krabbe’s disease, instead of glucosylceramidase, the lysosomal enzyme that is affected is galactosylceramidase (GALC gene)." (PMID 37998376, 2023). "Two AAV serotypes have been studied in clinical trials for Krabbe disease: AAVhu68 and AAVrh10 carrying the GALC gene." (PMID 36835039, 2023). "Since GALC overexpression is toxic to HSPCs, direct delivery of the AAV vectors to the CNS to deliver the GALC gene and restore enzyme activity for treatment of Krabbe disease has been proposed." (PMID 38004502, 2023). "Globoid cell leukodystrophy (GLD), also known as Krabbe disease, is a lysosomal storage disease that is triggered by a deficit of the lysosomal enzyme galactosylceramidase (GALC) and is characterized by psychosine (PSY) accumulation in the nervous system." (PMID 37076788, 2023). "The loci for the diseases for which GLBs have been reported are as follows: Werdnig-Hoffman disease, survival motor neuron 1 (SMN1) on 5q13.2; Krabbe disease, galactocerebrosidase (GALC) on 14q31.3; and 13q deletion syndrome, [46, XY, del (q22q31)]." (PMID 36447271, 2022). "Recent studies have shown that neuronal axons are both structurally and functionally compromised in Krabbe disease, even before demyelination, suggesting a possible neuron-autonomous role of GALC." (PMID 35789331, 2022). "To assess the role of GALC in neurons, and its relationship to the pathogenesis of Krabbe disease, we used a recently developed conditional Galc floxed mouse and a pan-neuronal–specific Syn1Cre mouse line (JAX#003966)." (PMID 35789331, 2022).